SPIRE1 (spire type actin nucleation factor 1)
Description:
Acts as an actin nucleation factor, remains associated with the slow-growing pointed end of the new filament. Involved in intracellular vesicle transport along actin fibers, providing a novel link between actin cytoskeleton dynamics and intracellular transport. Required for asymmetric spindle positioning and asymmetric cell division during meiosis. Required for normal formation of the cleavage furrow and for polar body extrusion during female germ cell meiosis. Also acts in the nucleus: together with FMN2, promotes assembly of nuclear actin filaments in response to DNA damage in order to facilitate movement of chromatin and repair factors after DNA damage. In addition, promotes innate immune signaling downstream of dsRNA sensing. Mechanistically, contributes to IRF3 phosphorylation and activation downstream of MAVS and upstream of TBK1.
Synonyms: Spir-1; KIAA1135
Tractability: Antibody: UniProt places it where antibodies can reach, with high confidence; its Gene Ontology location is reachable by antibodies, with medium confidence. PROTAC: its protein half-life has been measured.
Gene: Protein-coding gene on chromosome 18 (12,446,512 to 12,658,119, reverse strand). Ensembl gene ENSG00000134278.
Subcellular location: Cytoplasm, cytoskeleton; Cytoplasm, perinuclear region; Cell membrane; Cytoplasmic vesicle membrane
Subcellular location (Human Protein Atlas): Cytosol; Nucleoplasm; Plasma membrane
Gene Ontology:
Molecular function: protein binding; microtubule binding; actin binding
Biological process: actin cytoskeleton organization; establishment of meiotic spindle localization; formin-nucleated actin cable assembly; positive regulation of double-strand break repair; positive regulation of mitochondrial fission; actin filament network formation; cleavage furrow formation; Golgi vesicle transport; intracellular transport; polar body extrusion after meiotic divisions; vesicle-mediated transport; actin nucleation
Cellular component: cytosol; mitochondrial outer membrane; plasma membrane; cell cortex; cleavage furrow; cytoplasmic vesicle membrane; cytoskeleton; perinuclear region of cytoplasm
Genetic constraint (gnomAD): Loss-of-function variants: 31 observed, 68.1 expected, observed/expected ratio (o/e) 0.46, 90% interval 0.34 to 0.61. The upper end of that interval is the gene's LOEUF score, 0.61, which puts it in group 2 of 6, group 1 being the genes least tolerant of losing a copy. Missense variants: 752 observed, 816.86 expected, observed/expected ratio (o/e) 0.92, 90% interval 0.87 to 0.98. Synonymous variants: 349 observed, 315.66 expected, observed/expected ratio (o/e) 1.11, 90% interval 1.01 to 1.21.
Homologues: Orthologues: chimpanzee SPIRE1 (99% identical), macaque SPIRE1 (98% identical), rabbit SPIRE1 (92% identical), dog SPIRE1 (91% identical), mouse Spire1 (89% identical), rat Spire1 (88% identical), pig SPIRE1 (87% identical), tropical clawed frog spire1 (73% identical), zebrafish spire1a (62% identical), guinea pig SPIRE1 (60% identical), zebrafish spire1b (45% identical), Drosophila melanogaster spir (29% identical). Paralogues in human: SPIRE2 (40% identical).
Diseases named in the same sentence as SPIRE1 in open-access papers:
SPIRE1 is named in the same sentence as 8 diseases in open-access papers, as found by Europe PMC text mining. Sharing a sentence is not in itself a finding about the gene and the disease. The quoted sentences say what the papers report.
mental disorder (1 paper, 2022). A disease that has its basis in the disruption of mental process. "Eight genes are implicated in viral (SEC14L1, JMJD6, SRSF2, TMPRSS2, MX1, MX2) or bacterial (COL8A1, SPIRE1) infections, seven genes (MFSD11, METTL23, CTTNBP2, BACE2, IMPA2, MPPE1 and GNAL) are involved in mental disorders and one gene (MGAT5B) is related to the Golgi complex." (PMID 35581286, 2022).
periodontitis (1 paper, 2023). An acute or chronic inflammatory process that affects the tissues that surround and support the teeth. "Here, we identified miR-185-5p as a sponging target of LncRNA SPIRE1, and notably, as a pathogenic factor in periodontitis development, as its inhibition could significantly restore the impaired immunomodulation ability of mandibular BM-MSCs." (PMID 37490712, 2023). "In this study, we found that the mandibular BM-MSCs derived from the mice with induced periodontitis showed a higher expression level of LncRNA SPIRE1 than that from healthy mice." (PMID 37490712, 2023). "We found that mandibular BM-MSCs from P. gingivalis-induced periodontitis mice had significantly reduced expression of LncRNA SPIRE1 than that from normal control mice." (PMID 37490712, 2023). "In this study, we identified LncRNA SPIRE1 as an ncRNA that was significantly down-regulated in mandibular BM-MSCs from periodontitis mice, and knockdown of LncRNA SPIRE1 from normal mandibular BM-MSCs recapitulated their counterparts in periodontitis mice in term of inducing Th17/Treg imbalance." (PMID 37490712, 2023). "In addition, mandibular BM-MSCs from the periodontitis mice displayed obviously increased expression of miR-181a-5p than that from the normal mice, further consolidating the targeting relationship between LncRNA SPIRE1 and miR-181a-5p." (PMID 37490712, 2023). "Notably, targeted knockdown of LncRNA SPIRE1 or PRLR or transfection of miR-181a-5p mimics activated the JAK/STAT3 signaling in normal BM-MSCs, while treatment with STAT3 inhibitor C188-9 restored the immunomodulatory properties of periodontitis-associated BM-MSCs." (PMID 37490712, 2023). "To further evaluate the in vivo benefits of targeted regulation of the LncRNA SPIRE1/miR-181a-5p/PRLR axis in immune modulation, we investigated the immunosuppressive properties of mandibular BM-MSCs after gene manipulations in LPS-induced experimental periodontitis mouse model." (PMID 37490712, 2023).
Ventriculomegaly (1 paper, 2016). An increase in size of the ventricular system of the brain. "Fetus 8, diagnosed with ventriculomegaly, carried a 0.19-Mb deletion of chromosomal region 18p11.21 comprising most of the SPIRE1 gene." (PMID 27087860, 2016).
cancer (3 papers, 2019 to 2022). A tumor composed of atypical neoplastic, often pleomorphic cells that invade other tissues. "YIPF6, TMEM9, and PSME3 have been associated with cancer and SPIRE1 reportedly contributes to metastatic potential." (PMID 30913233, 2019). "This suggests that the alternative inclusion of this previously unknown region in SPIRE1 transcript may be a common feature across different cancer types in vitro and in vivo." (PMID 36304260, 2022). "Notably, the presence of a differentially expressed non-annotated exon between exon 12 and 13 in SPIRE1, which we detected in cancer cell lines, was also identified in BRCA, LUAD, KIPAN, PRAD, and THCA cohorts by DJEC DB data using gene-wise splicing visualization." (PMID 36304260, 2022).
infection (3 papers, 2016 to 2024). The state of being infected such as from the introduction of a foreign agent such as serum, vaccine, antigenic substance or organism. "Our analysis of S. TmSipA (SL1344, sopBsopEsopE2) identified roles for Spire1 and Spire2 in different steps of the infection process." (PMID 27627128, 2016). "At any rate, the functional differences detected between SPIRE1 and SPIRE2 in the HeLa Kyoto and the iMEF infection assays might be of general interest, as earlier studies of SPIRE proteins have not detected significant functional differences between the different family members." (PMID 27627128, 2016). "Interestingly, SPIRE2 (but not SPIRE1) has recently been shown to promote the efficiency of host cell infection by Listeria monocytogenes." (PMID 27627128, 2016).
neurological disorders (1 paper, 2022). "Indeed, identified genes are implicated in viral (SEC14L1, JMJD6, SRSF2, TMPRSS2, MX1, MX2) bacterial (COL8A1, SPIRE1), and neurological disorders (MFSD11, METTL23, CTTNBP2, BACE2, IMPA2, MPPE1 and GNAL), or in the functions of the Golgi complex (MGAT5B), organelle where viral envelope is occurred." (PMID 35581286, 2022).
SPIRE1 also shares sentences with these, for which no sentence is quoted: tumor (2 papers); virus infection (1).